EGFR (epidermal growth factor receptor)
Diseases named in the same sentence as EGFR in open-access papers (continued):
Sharing a sentence is not in itself a finding about the gene and the disease.
non-small cell lung carcinoma (continued). "Non-small-cell lung cancers (NSCLCs) caused by activating mutations in the kinase domain of epidermal growth factor receptor (EGFR) initially respond to first-generation reversible drugs gefitinib and erlotinib." (PMID 28881827, 2017). "Epidermal growth factor receptor (EGFR) tyrosine kinase inhibitors (TKIs) have obtained excellent therapeutic effects against non-small cell lung cancer (NSCLC) harboring activating EGFR mutations." (PMID 29179454, 2017). "EGFR mutation subtype is a recognised factor impacting outcomes of patients receiving oral tyrosine kinase inhibitors (TKIs) in non-small-cell lung cancer (NSCLC)." (PMID 29104613, 2017). "Conversely, overexpression and abnormal activation of EGFR is associated with varieties of human epithelial malignancies, especially non-small cell lung cancer (NSCLC)." (PMID 28630494, 2017). "Gefitinib (Iressa) is a TKI that specifically targets EGFR and has been used to treat non-small cell lung cancers with EGFR mutations." (PMID 28881753, 2017). "Targeted therapy with epidermal growth factor receptor tyrosine kinase inhibitor (EGFR-TKIs) is regarded as the main accepted first-line treatment on EGFR mutation in non-small cell lung cancer (NSCLC)." (PMID 28302223, 2017). "We previously discovered a common 2,903-base pair (bp) deletion polymorphism in the BIM gene that contributed to response heterogeneity in patients with CML and epidermal growth factor receptor-mutated non-small cell lung cancer (EGFR-NSCLC)." (PMID 29100409, 2017). "Targeted agents such as erlotinib or gefitinib (EGFR inhibitor) or crizotinib or ceritinib (ALK inhibitors) have shown activity in NSCLC (non-small cell lung cancer) which possess these putative types of mutation." (PMID 28819582, 2017). "Advanced EGFR mutation-positive non-small cell lung cancer patients presenting with significant weight loss (>10.0%) and brain metastases had a shorter PFS." (PMID 29163842, 2017). "The use of epidermal growth factor receptor tyrosine kinase inhibitors (EGFR-TKIs) in the treatment of sensitive EGFR mutation in non-small cell lung cancer (NSCLC) has been proved significant curative effect." (PMID 29061221, 2017). "We describe two patients who underwent residual tumor resection after responding to EGFR-TKIs for advanced non-small cell lung cancer (NSCLC) harboring EGFR gene mutations, along with a review of the literature." (PMID 29169381, 2017). "Patients with non-small cell lung cancer harboring activating EGFR mutations who were scheduled to undergo EGFR-tyrosine kinase inhibitors (EGFR-TKIs) were enrolled between September 2011 and March 2015." (PMID 29029416, 2017). "One study compared ctDNA to tissue based NGS for EGFR mutations, instead of a comprehensive panel, in patients with non-small cell lung cancer and found a concordance rate of 88%." (PMID 28431395, 2017). "Activating mutations in the epidermal growth factor receptor (EGFR) gene define one of the most common molecular subtypes of non-small cell lung cancers." (PMID 29119113, 2017). "Then, this PCR-SERS method was used on the plasma of 48 patients with non-small cell lung cancer (NSCLC) to detect EGFR mutations." (PMID 28684733, 2017). "A significant proportion of non-small cell lung cancers (NSCLCs) carry epidermal growth factor receptor (EGFR) gene mutations, which have been identified in approximately 10–30% of NSCLCs." (PMID 29285266, 2017). "Some clinical characteristics (Asian origin, never smoked, female gender and histologic adenocarcinoma subtype) are associated with the presence of EGFR mutations in patients with non-small cell lung cancer (NSCLC)." (PMID 28832323, 2017). "In non-small cell lung cancer it was shown that ALK rearrangements (that were previously thought to be mutually exclusive with activating EGFR and KRAS mutations) can be found together with EGFR mutations in rare cases." (PMID 28549417, 2017).
non-small cell lung carcinoma (continued). "Non-small-cell lung cancer patients with activating epidermal growth factor receptor (EGFR) mutations typically benefit from ﻿EGFR tyrosine kinase inhibitor treatment." (PMID 28871105, 2017). "Compared to cytotoxic chemotherapy, afatinib has been shown to have better efficacy in the treatment of non-small cell lung cancer harboring EGFR mutations." (PMID 29237484, 2017). "The diagnostic utility of ctDNA for the detection of epidermal growth factor receptor (EGFR) mutations harbored in tumors of patients with advanced non-small-cell lung cancer (NSCLC) is supported by the results of several large studies/meta-analyses." (PMID 27980215, 2017). "Epithelial-mesenchymal transition (EMT) is clinically associated with acquired resistance to epidermal growth factor receptor (EGFR) tyrosine kinase inhibitors (TKI) in non-small cell lung cancers (NSCLC)." (PMID 29190911, 2017). "IL-8 protein and IL-8 mRNA markers for oral cancer, non-squamous cell lung cancer (NSCLC) oncogenic mutation, and epidermal growth factor receptor (EGFR) mutation in non-small cell lung cancer can be detected through this EFIRM system." (PMID 28677648, 2017). "Compared to wild-type EGFR, EGFRs with activating mutations in non-small cell lung cancers display higher binding to RTKIs, leading to 100-fold greater sensitivity to RTKIs31." (PMID 28593948, 2017). "Vorinostat, an FDA-approved HDACi, was effective in overcoming BIM deletion polymorphism-induced TKI resistance in non-small-cell lung cancer (NSCLC) when combined with an EGFR TKI." (PMID 28301600, 2017). "In this population, EGFR mutations were identified in 50.33% (1054) of 2094 surgically resected non-small cell lung cancers, and 321 patients with an EGFR exon 19 deletion and 372 patients with exon 21 L858R were identified." (PMID 29110716, 2017). "This was proven true in many cases: Gleevec for chronic myeloid leukemia (CML) and gastrointestinal stromal tumors (GIST), Gefitinib for non-small cell lung cancer carrying hyperactive and mutated EGFR, and Vemurafenib for melanoma." (PMID 28445125, 2017). "It has recently been shown that inhibition of JAKs attenuates growth of small cell lung cancers in vitro and in vivo, and that activation of JAK signaling induces resistance to EGFR mutations in non-small cell lung cancers." (PMID 28118365, 2017). "In this survival update, single-agent erlotinib achieved a median overall survival of more than 3 years in patients with EGFR mutation-positive non-small-cell lung cancer." (PMID 27659294, 2017). "Epidermal growth factor receptor mutation analysis in non-small cell lung cancer is important for selecting patients who will receive treatment with tyrosine kinase inhibitors." (PMID 28832323, 2017). "When such resistance is induced by a clear secondary mutation, such as a secondary EGFR T790M mutation in non-small-cell lung cancer, targeted use of an appropriate secondary inhibitor can be highly effective." (PMID 28059068, 2017). "The presence of EGFR activating mutations is an established predictive biomarker in non-small cell lung cancer (NSCLC) with in-frame deletions of exon 19 (E746_A750) and L858R substitution in exon 21 accounting for > 90% of all activating mutations." (PMID 28881608, 2017). "It is well established that EGFR is amplified and/or mutated in gliomas and non-small-cell lung carcinoma while HER2 is amplified and/or over-expressed in breast, gastric, ovarian, non-small cell lung carcinoma, and several other tumor types." (PMID 29371993, 2017). "EGFR inhibitors were used to treat not only non-small-cell lung cancer with EGFR mutation, but also cancer with overexpression of EGFR." (PMID 28316978, 2017). "Approximately 50% of non-small cell lung cancer (NSCLC) patients with epidermal growth factor receptor (EGFR) mutations, such as exon 19 deletion and L858R point mutation, receive tyrosine-kinase inhibitors (TKIs) as their first-line treatment." (PMID 28683123, 2017).
non-small cell lung carcinoma (continued). "Epidermal growth factor receptor (EGFR) T790M acquired drug-resistance mutation has become a major clinical challenge for the therapy of non-small cell lung cancer." (PMID 28630494, 2017). "Even if cfDNA analysis tends to become a gold standard for targetable driver mutation detection (especially for EGFR mutation in metastatic Non-Small Cell Lung Cancer), high throughput analysis such as whole exome sequencing have been poorly reported." (PMID 29161279, 2017). "Non-small cell lung carcinomas (NSCLC) commonly harbor oncogenic mutations in the EGF receptor (EGFR), resulting in constitutive activation." (PMID 28915640, 2017). "In Japan, the clinical efficacy of erlotinib monotherapy in epidermal growth factor receptor (EGFR) mutation-positive non-small-cell lung cancer was demonstrated in the phase II JO22903 trial, which reported a median progression-free survival of 11.8 months." (PMID 27659294, 2017). "In recent years, targeted therapy of epidermal growth factor receptor-tyrosine kinase inhibitor (EGFR-TKIs) is the leading treatment modality for patients with advanced non-small cell lung cancer (NSCLC) and EGFR gene mutation." (PMID 29167008, 2017). "We aimed to identify a panel of circulating plasma microRNAs that can predict EGFR mutation status and monitor epidermal growth factor receptor-tyrosine kinase inhibitor treatment in patients with non-small cell lung cancer." (PMID 28496005, 2017). "Non-small-cell lung carcinomas with activating mutations in epidermal growth factor receptor (EGFR) frequently respond to treatment with tyrosine kinase inhibitors targeting EGFR, but the responses are not durable, as tumors acquire resistance." (PMID 28677655, 2017). "Resistance to EGFR-tyrosine kinase inhibitors in non-small-cell lung cancer is mediated by the C797S/T790M/activating mutation." (PMID 28287083, 2017). "Discovery of the epidermal growth factor receptor gene mutation and the anaplastic lymphoma kinase chromosomal translocation in non-small cell lung cancer has prompted efforts around the world to identify many less common targetable oncogenic drivers." (PMID 29034207, 2017). "Epidermal growth factor receptor (EGFR) mutations predict better outcomes with EGFR tyrosine kinase inhibitors in patients with non-small cell lung cancer (NSCLC)." (PMID 28827701, 2017). "On the other hand, blocking glycolysis sensitizes non-small cell lung cancer cells with a T790M mutation to the treatment with irreversible EGFR inhibitors." (PMID 27926487, 2017). "EGFR mutations are found in 10% of non small cell lung cancer (NSCLC) in Caucasians and 40% in Asians." (PMID 29285237, 2017). "Epidermal Growth Factor Receptor (EGFR) mutated Non Small Cell Lung Cancers (NSCLCs) are a molecularly subgroup of patients with peculiar clinic-pathological characteristics." (PMID 28060728, 2017). "Treatment with EGFR inhibitors is limited to patients with advanced/metastatic non-small cell lung cancer who have known EGFR mutations." (PMID 29262544, 2017). "For instance, patients with non-small cell lung cancers treated with an EGFR inhibitor to target an EGFR mutation nearly always develop resistance, due to secondary mutations." (PMID 26848768, 2016). "These mutations account together for more than 90% of activating EGFR mutations and are present in about 10% of Caucasian patients with non-small-cell lung cancer (NSCLC) and about 50% of Asian patients with NSCLC." (PMID 27433281, 2016). "Gefitinib is a selective tyrosine kinase inhibitor of the epidermal growth factor receptor (EGFR) used to treat adults with EGFR mutation-positive non-small-cell lung cancer (NSCLC)." (PMID 26945426, 2016). "Currently, molecular-based targeted therapy is a standard approach in selected patients such as non-small cell lung cancer (NSCLC) with EGFR mutations in which a very high response rate of approximately 75% is observed." (PMID 27105424, 2016).
non-small cell lung carcinoma (continued). "Diagnostic techniques for epidermal growth factor receptor (EGFR) mutations are important in treatment of advanced non-small cell lung cancer (NSCLC) thanks to the availability of tyrosine-kinase inhibitors (TKIs)." (PMID 27483001, 2016). "A total of 264 advanced non-small-cell lung cancer (NSCLC) patients with sensitive mutations received EGFR TKI therapy as the first-line therapy, and a total of 187 patients received TKI as the second-line therapy at Shanghai Chest Hospital." (PMID 27637087, 2016). "EGFR TKIs are effective in non-small cell lung cancer (NSCLC) patients with an activating mutation of the EGFR TK domain." (PMID 27004400, 2016). "Epidermal Growth Factor Receptor (EGFR) tyrosine-kinase inhibitors (TKIs) have changed treatment strategies for patients with advanced non-small-cell lung cancer (NSCLC) harbouring mutations in EGFR gene." (PMID 27206674, 2016). "This set of instances includes the wild-type EGFR kinase domain and EGFR kinase domain with mutations, which are involved in types of cancer like non-small cell lung cancer." (PMID 27869781, 2016). "Gefitinib is generally regarded as a relatively safe agent, and several reports have described its efficacy in patients with epidermal growth factor receptor mutation-positive non-small cell lung cancer and a poor performance status." (PMID 26724810, 2016). "AZD9291 (osimertinib, tagrisso) has been approved for treatment of the metastatic EGFR T790M mutation-positive non-small cell lung cancer." (PMID 27448564, 2016). "Gefitinib is a first line anti-tumor drug used for the treatment of patients with non-small cell lung cancer (NSCLC) harboring EGFR mutations." (PMID 27690301, 2016). "Epidermal Growth Factor Receptor (EGFR) Tyrosine Kinase Inhibitors (TKIs) are frontline therapy for advanced or metastatic non-small cell lung cancer (NSCLC) with sensitizing EGFR mutations such as exon 19 deletion or exon 21 L858R mutation." (PMID 27467256, 2016). "Epidermal growth factor receptor (EGFR) mutations are found in approximately 30% of patients with advanced non-small cell lung cancer (NSCLC) in East Asia and in 10–15% of such patients in Western countries." (PMID 26883083, 2016). "Epidermal growth factor receptor (EGFR), a member of the c-erbB family, is highly expressed in a variety of human tumors, including non-small cell lung cancer (NSCLC), and is implicated in tumor development." (PMID 26824318, 2016). "This retrospective study explored the efficacy and safety of this combined regimen in patients with EGFR mutation and advanced non-small cell lung cancer (NSCLC)." (PMID 27655708, 2016). "Non-small cell lung cancer (NSCLC) patients with activating epidermal growth factor receptor (EGFR) mutations initially respond well to the EGFR tyrosine kinase inhibitors (TKIs) erlotinib and gefitinib." (PMID 26848869, 2016). "Patients with advanced non-small-cell lung cancer (NSCLC) harboring sensitive epithelial growth factor receptor (EGFR) mutations invariably develop acquired resistance to EGFR tyrosine kinase inhibitors (TKIs)." (PMID 27528220, 2016). "Epidermal growth factor receptor (EGFR) mutations in non-small cell lung cancer (NSCLC) are a response to EGFR-tyrosine kinase inhibitor." (PMID 27472739, 2016). "Epidermal growth factor receptor (EGFR) mutation status is regarded as a particularly important element for improving non squamous non-small cell lung cancer (NSCLC) prognosis." (PMID 27215400, 2016). "The detection of epidermal growth factor receptor (EGFR) tyrosine kinase inhibitor (TKI)-sensitizing mutations is important in guiding the treatment of advanced non-small cell lung cancer (NSCLC)." (PMID 27685950, 2016). "The mechanism by which non-small cell lung cancer (NSCLCs) with activating EGFR mutations become resistant to tyrosine kinase inhibitors (TKIs) is the second mutation in EGFR and/or the activation of the C-met pathway." (PMID 28036020, 2016).
non-small cell lung carcinoma (continued). "Epidermal growth factor receptor-tyrosine kinase inhibitors (EGFR-TKIs) show a clinical benefit when used to treat patients with EGFR-mutated non-small-cell lung cancer (NSCLC), but this treatment unfortunately fails in patients with TKI-resistant tumors." (PMID 27362807, 2016). "As a first-line treatment for advanced EGFR mutation-positive non-small cell lung carcinoma, Erlotinib was found to be superior to standard chemotherapy and conferred a better progression-free survival in patients." (PMID 27509178, 2016). "Factors associated with EGFR testing among patients diagnosed in 2010 with stage IV non-small cell lung cancer, Patterns of Care." (PMID 27294665, 2016). "Anaplastic lymphoma kinase (ALK) rearrangements, found in approximately 5 % of non-small cell lung cancers (NSCLCs), are relatively rare genetic alterations compared with epidermal growth factor receptor (EGFR) or KRAS mutations." (PMID 27756333, 2016). "Another commonly used drug in treating non-small cell lung cancer (NSCLC) patients with epidermal growth factor receptor (EGFR) gene mutation is Erlotinib." (PMID 27225309, 2016). "Despite the benefit of epidermal growth factor receptor-tyrosine kinase inhibitors (EGFR-TKIs) in non-small cell lung cancer (NSCLC) patients with EGFR mutation, acquired resistance to these therapies is a critical clinical problem." (PMID 26789630, 2016). "Firstly, activating mutations in EGFR confer exquisite sensitivity to EGFR TKIs in non-small cell lung cancer, with cell lines harbouring these mutations being 10 to 50-fold more sensitive to gefitinib." (PMID 27907909, 2016). "Mutations such as G719S, L858R, T790M, G719S/T790M or T790M/L858R can alter the kinase activity of EGFR by disrupting autoinhibitory interactions, which are associated with different drug responses from non-small cell lung cancer patients." (PMID 27869781, 2016). "The epidermal growth factor receptor (EGFR)-targeting tyrosine kinase inhibitors (TKIs) have shown remarkable benefits in non-small cell lung cancer (NSCLC) patients with drug-sensitive mutations in the EGFR gene." (PMID 27835586, 2016). "This feedback mechanism is consistent with the rapid rewiring of signaling networks associated with adaptive resistance to EGFR inhibitors in non-small-cell lung cancer." (PMID 27650546, 2016). "Osimertinib (OSI, also known as AZD9291) is the newest FDA-approved epidermal growth factor receptor (EGFR) tyrosine kinase inhibitor for non-small cell lung cancer (NSCLC) patients with EGFR T790M mutation." (PMID 27835594, 2016). "Recent advancements in EGFR mutation targeted therapy led to a major paradigm shift in the treatment of non-small cell lung cancer." (PMID 27623437, 2016). "Discovery of certain epidermal growth factor receptor (EGFR) mutations that affect tyrosine kinase inhibitor (TKI) efficacy in non-small cell lung carcinoma (NSCLC) has increased the importance of identifying patients harboring EGFR mutations." (PMID 26979333, 2016). "For example, in non-small cell lung cancer, mutation within the kinase domain of EGFR and epithelial–mesenchymal transition are responsible for the development of resistance to gefitinib." (PMID 26904540, 2016). "A decision tree model was employed to select the appropriate treatment regimen according to the results of EGFR mutation testing and a Markov model was constructed to simulate disease progression of advanced non-small cell lung cancer." (PMID 27483001, 2016). "The two main mechanisms of resistance to EGFR tyrosine kinase inhibitors (TKIs) in non-small cell lung cancer (NSCLC) are the occurrence of T790M secondary mutation in the kinase domain of EGFR and MET amplification." (PMID 27726115, 2016). "Some previous systematic reviews were published reporting the prevalence of EGFR mutation in patients with non-small cell lung cancer." (PMID 27738317, 2016).